PAX6 (paired box 6)
Diseases named in the same sentence as PAX6 in open-access papers (continued):
Sharing a sentence is not in itself a finding about the gene and the disease.
squamous cell carcinoma (1 paper, 2013). A carcinoma arising from squamous epithelial cells. "In the oral mucosa, IL-6 mediated inflammation promotes squamous cell carcinoma through the hypermethylation of Pax6, suggesting epigenetic gene silencing may be an important consequence of chronic inflammation during tumorigenesis." (PMID 24143217, 2013).
subependymoma (1 paper, 2010). Subependymoma is a rare and slow growing type of ependymoma, often presenting in middle-aged adults, found more commonly in men than in women, usually located in the fourth and lateral ventricles and manifesting with variable symptoms including headache, nausea, and loss of balance. "Collectively, we speculate that the defect in PAX6 may have contributed to the extremely large size of the subependymoma, due to a loss of tumor suppressor activity in glial cell lineage." (PMID 20500513, 2010). "Therefore, the currently detected deletions of PAX6 are unlikely to be responsible for the subependymoma onset." (PMID 20500513, 2010). "The subependymoma had an additional de novo deletion spanning from the intron 4 to intron 6 of PAX6, although we could not completely determine whether these two deletions are on the same chromosome or not." (PMID 20500513, 2010).
substance abuse (1 paper, 2025). The use of a drug for a reason other than which it was intended or in a manner or in quantities other than directed. "In terms of substance abuse, consistent with our observations, rats self-administering cocaine also displayed decreased Pax6 expression in the PFC." (PMID 41002437, 2025).
teratocarcinoma (1 paper, 2019). A germ cell tumor characterized by the presence of an embryonal carcinoma component and a teratoma component. "However, the expression levels of the pluripotency markers Oct4 and Nanog and lineage-specific gene markers Mvh, Gata4, Pax6 and Bry significantly differ between pluripotent stem and teratocarcinoma cells." (PMID 31143371, 2019).
uveal melanoma (1 paper, 2017). A melanoma derived from melanocytes of the uveal tract. "The lncRNA PAX6 upstream antisense RNA (PAUPAR) was found in uveal melanoma tissues and uveal melanoma cell lines at low levels, suggesting that it might act as a tumor suppressor lncRNA." (PMID 28350340, 2017).
viral infections (1 paper, 2016). "To test whether the PAX6 methylation in HCC tissues was associated with different virus infections, we analyzed the methylation level in 29 normal controls (NC) and 160 paired HCC tissues and their adjacent non-tumor tissues." (PMID 27110298, 2016). "The quantitative methylation level of PAX6 was higher in HCC tissues than that in corresponding non-tumor liver tissues irrespective of the virus infection background." (PMID 27110298, 2016).
Walker–Warburg syndrome (1 paper, 2024). "Nevertheless, coloboma has been associated with many genes, such as PAX6 and GDF6; and with many brain malformation syndromes such as Joubert syndrome, Aicardi syndrome, and Walker–Warburg syndrome." (PMID 38322500, 2024).
ZIKV infection (1 paper, 2019). "Cells also expressed PAX6, a marker of the early ectoderm, thus indicating that ZIKV infection did not impair the differentiation process." (PMID 31671583, 2019).
Zinc deficiency (1 paper, 2019). A deficiency of the essential metal Zinc; an essential cofactor for many enzymes. "Thus, not only ERK1/2 but also Sox2 and Pax6 downregulation at a period of active progenitor proliferation can contribute to the decrease in the number of fetal brain NPCs as a consequence of maternal marginal zinc deficiency." (PMID 30890920, 2019).
tumor (101 papers, 2009 to 2026). "PAX3, PAX5, and PAX8 are mainly associated with immune checkpoint expression, including PD-L1 and TIGIT, while PAX6 is linked to microsatellite instability and tumor mutational burden, implicating it in genomic dysregulation." (PMID 41752124, 2026). "Conversely, PAX6 reactivity displayed an inverse association with tumor grade (p = 0.035) and tumor size (p = 0.056)." (PMID 40553402, 2025). "As a tumor suppressor, PAX6 has been associated with epigenetic modulation, such as methylation of its promoter." (PMID 40506992, 2025). "Dysregulation of PAX6 expression has been implicated in a variety of human cancers, resulting in tumor suppressive or oncogenic phenotypes depending on the cellular context." (PMID 35081118, 2022). "In both organs, the maintenance of Pax6 expression during adult stages associates with a failure to undergo differentiation and to tumor development." (PMID 25695251, 2015). "There are several reports demonstrating that deletions of tumor‐related regions of PAX6 or dominant negative activity generated by PAX6 mutations are associated with tumors of glial cell origin." (PMID 20500513, 2010). "This pattern of NKX2.2 transcript expression was recapitulated in tumor samples, and was associated with high levels of PAX6 transcript in cell lines and tumors." (PMID 21059263, 2010). "To examine mutations of the PAX6 gene, we performed direct sequencing of all the exons and exon/intron boundaries of the gene using DNA from the patient's tumor tissue and lymphocytes." (PMID 20500513, 2010). "While no prior reports directly demonstrate that PAX6 regulates ferroptosis in tumor cells, studies have been reported to indirectly support the involvement of PAX6 in redox regulation." (PMID 41154694, 2025). "The paired-box gene 6 (PAX6), a transcription factor, is known for its essential roles in embryonic development, ocular morphogenesis, and tumor progression." (PMID 41154694, 2025). "In the context of cancer, PAX6’s real nature is long way away from being understood, as it exhibits dual functionality, acting either as a tumor suppressor or a promoter of tumor progression depending on the molecular and cellular environment." (PMID 40506992, 2025). "PAX6 exhibits dual regulatory roles in cancer, with its dysregulated expression contributing to tumor development." (PMID 41154694, 2025). "To verify the effect of PAX6 on tumor growth in vivo, we performed castration on 6–8 weeks old male nude mice." (PMID 38745318, 2024). "The oncogenic factor paired-box 6 (PAX6) of BC belongs to a family of cassette transcription factors that can influence the behavior of tumor cells." (PMID 37588204, 2024). "In recent years, accumulating evidence has also shed light on the multifaceted role of PAX6 in tumorigenesis and tumor progression, revealing its remarkable contribution to the pathological processes." (PMID 38745318, 2024). "YAP1–MAMLD1 gene fusion‐driven neuroepithelial tumours demonstrating hyperproliferation showed an increase in Yap1 expression, which correlated with an increase in Pax6." (PMID 36656098, 2023). "In a controversial study, PAX6-knock out human neuronal epithelioma cells display increased proliferation and colony-forming abilities, indicating that PAX6 functions as a tumor suppressor." (PMID 35682795, 2022). "All but one (11 of 12) of PAX6 mutations were in the MSI subgroup; the PAX6X306_splice mutation was present in a CN-low tumor." (PMID 35081118, 2022). "PAX6 has a very strong neurogenic role, and its expression has been found to work as a tumor suppressor gene in GBM." (PMID 35538578, 2022). "We show that TNFRSF9 inhibits tumor progression by suppressing p38 phosphorylation and the protein expression of the downstream target of p-p38 and PAX6." (PMID 35799609, 2022). "qRT-PCR assays were performed to evaluate the mRNA expression of TNFRSF9 and PAX6 in the tumor tissues." (PMID 35799609, 2022).
tumor (continued). "This syndrome is caused by large chromosomal deletions in chromosome 11p13, including PAX6 and the Wilms tumor gene (WT1), this genotype represents 10% of all classical aniridia cases." (PMID 34065151, 2021). "Among other mRNAs and pathways, miRNA-664 target paired box protein 6 (PAX6) involved in some neoplastic diseases, and miRNA-147 that inhibits cell proliferation and regulates the ER-Stress-induced apoptosis." (PMID 33982668, 2021). "PAX6 mRNA or protein was upregulated in six paired fresh GC samples compared to that in adjacent non‐tumor tissues (6/8, 75%)." (PMID 34459131, 2021). "The median tumor size was slightly larger in the low than in the high PAX6 expression group (18.6 mm vs. 15.5 mm, p = 0.24)." (PMID 33182335, 2020). "We indeed focused on two PAX motifs, PAX5 and PAX6 that have been known as tumor suppressive and oncogenic, respectively." (PMID 32693820, 2020). "Then protein levels of paired box genes (Pax-4 and Pax-6) were examined by western blotting, which were considered to promote tumor growth." (PMID 31636510, 2019). "To detect targets of PAX6, we used the Human Tumor Metastasis RT2 Profiler PCR Array, which contains 84 primer pairs that amplify genes involved in human metastasis." (PMID 31024010, 2019). "To investigate the molecular mechanism through which PAX6 is associated with NSCLC metastasis, we used the Human Tumor Metastasis RT2 Profiler PCR Array." (PMID 31024010, 2019). "Compared to the control group, PAX6 knockdown significantly restored CDDP efficacy as evidenced by decreases in tumor volume and weight." (PMID 31024010, 2019). "Similar findings were observed in apoptosis assays, wherein A549/PAX6 tumor cells exhibited a lower rate of apoptosis and were resistant to CDDP treatment." (PMID 31024010, 2019). "It is possible that in patients with node-positive disease, PAX6 decelerates further dissemination of the tumour and thus improves survival." (PMID 29568088, 2018). "Previous reports describing PAX6 expression in human malignancies dealt with tumours of brain and pancreas, which are the organs with tight developmental links to PAX6." (PMID 29568088, 2018). "The large majority of super enhancers were tumor-specific and enriched for tumor-related genes, such as PAX6, FGFRL1, FGFR1, SKI, and BOC." (PMID 30279357, 2018). "The knock out cells had increased proliferation and colony forming abilities compared to wild type cells, consistent with clinical observations indicating that PAX6 functions as a tumor-suppressor." (PMID 29716531, 2018). "There were a lot of low grade, but significant correlations, when the PAX6 expression was compared with tumour cell expression of molecular markers previously published by our group." (PMID 29568088, 2018). "Inhibition of cancer cell migration by PAX6 fits well with the proposed tumour-suppressor role and with our survival data in pN+ patients." (PMID 29568088, 2018). "It has been shown that PAX6 is expressed in a number of different cancer cell lines, and that it can act as a tumor suppressor or in an oncogenic manner, depending on the tissue affected." (PMID 29716531, 2018). "PAX6 functions as either oncogene or tumor suppressors which seem to be tissue specific and is discussed controversially." (PMID 27110298, 2016). "The methylation levels of the PAX6 gene were significantly increased in HCV-positive HCC tissues (p < 0.0001) as compared with their adjacent non-tumor tissues." (PMID 27110298, 2016). "The inhibition of PAX6 reduced tumor cell apoptosis (P<0.05, n=3), but induced cell cycle S phase arrest (SO-Rb50; P<0.05, n=3) and G2/M phase arrest (Y79; P<0.05, n=3)." (PMID 24939714, 2014). "miR-223 was found promoted the growth and invasion of tumor cells by targeting tumor suppressor PAX6 and FBXW7/hCdc4." (PMID 25329674, 2014). "VEGFA, a growth factor and MMP2, a cellular matrix protein, involved in tumor formation and metastasis are found repressed by Pax6." (PMID 23056534, 2012).
tumor (continued). "We also examined the underlying mechanisms and detected a deletion in the 5′‐region of PAX6 in lymphocytes and tumor cells and an additional de novo deletion in the tumor cells from the patient." (PMID 20500513, 2010). "To analyze the genetic mechanisms of tumorigenesis, we first examined the paired box 6 (PAX6) gene using both tumor tissue and peripheral lymphocytes." (PMID 20500513, 2010). "Amongst the primary tumor samples, 20/27 (74%) samples showed low expression of PAX6 as compared to normal adult brain tissue." (PMID 21059263, 2010). "Similarly, SNHG17 has been identified as a sponge for miR-375, indirectly promoting PAX6 expression and contributing to tumor proliferation and metastasis." (PMID 40076805, 2025). "Consistent with this notion, we noted that PAX6 correlated with smaller tumor size and lower grade." (PMID 40553402, 2025). "Notably, over-expression of PAX6 in LNCaP and C42B cells accelerated cell proliferation, colony formation and tumor sphere formation in LNCaP and C42B cells after ENZ treatment (20 μM)." (PMID 38745318, 2024). "On the other hand, since a negative-loop feedback regulation between two genes was well-reported to be involved in the regulation of tumor progression, we herein investigated whether PAX6 could also regulate the transcription of AR as feedback." (PMID 38745318, 2024). "GBM has also been found to induce WNT5A to mediate tumor cell differentiation into endothelium-like cells via the PAX6/DLX5 transcription program, and subsequently recruit peripheral endothelial cells, which form pseudo-blood vessels, thereby facilitating tumor-invasive growth." (PMID 36880534, 2023). "In 2003, the expression of PAX6 mRNA was first shown in various tumor cell lines." (PMID 36313570, 2022). "Although we have identified regulatory mechanisms of the ZFPM2-AS1/miR-511-3p/PAX6 axis in RB progression, the mechanism by which downregulation of PAX6 inhibits tumor progression remains unclear." (PMID 34989314, 2022). "MiR-383 may act as a tumor-inhibiting factor for CRC by directly targeting PAX6 to suppress cell invasion and proliferation." (PMID 35168468, 2022). "In CRC, miR-383 can operate as a tumor suppressor by attenuating PAX6 expression." (PMID 36313570, 2022). "A previous study demonstrated that circFOKX2 not only interacts with YBX1 and hnRNPK to elevate the expression of the oncogenes NUF2 and PDXK but also functions as a sponge for miR-942 to upregulate the expression of ANK1, GDNF, and PAX6, which contribute to tumor progression in PDAC." (PMID 34419070, 2021). "Moreover, the expression levels of PAX6 were significantly correlated with multiple pathological variables, including tumor size (p = 0.008), differentiation state (p = 0.003), clinical stage (p < 0.001), and metastasis (p = 0.001)." (PMID 34459131, 2021). "However, we cannot fully exclude the possibility that PAX6 expression is suppressed by 5‐Aza, as hypermethylation of PAX6 contributes to various tumor types." (PMID 34459131, 2021). "Therefore, PAX6 can act as a tumor suppressor or in an oncogenic manner, depending on the tissue type." (PMID 34459131, 2021). "A recent study suggested that CDK4/6 inhibitors could downregulate DNMT1 expression in Treg cells and trigger anti‐tumor immunity, suggesting that targeting PAX6 might be of clinical value to tumor immunotherapy in the future." (PMID 34459131, 2021). "Interestingly, two PAX motifs, PAX5 (tumor suppressive) and PAX6 (oncogenic), were frequently found in hyper- and hypomethylated intron DMRs, respectively." (PMID 32693820, 2020). "PAX6 was significantly upregulated in tumor tissues compared to normal lung tissues." (PMID 31024010, 2019). "PAX6 upregulates a known tumor suppressor PTEN, as well as SFRP2 - an inhibitor of the WNT pathway." (PMID 29568088, 2018). "PAX6 is a transcription factor with a proposed tumour suppressor function." (PMID 29568088, 2018).
tumor (continued). "Further studies should dissect the molecular mechanisms explaining the tumour-suppressive action of PAX6, as well as evaluate whether its expression may predict response to anticancer therapy such as platinum-based therapy and novel targeted therapies." (PMID 29568088, 2018). "Again, this is in line with our concept that PAX6 acts as a tumour suppressor in NSCLC." (PMID 29568088, 2018). "PAX6 exerts a tumor suppressor effect and is frequently silenced by promoter methylation in human cancers, including bladder, breast, gastric, and non-small cell lung cancer, suggesting that it may play a role in carcinogenesis." (PMID 27110298, 2016). "PAX6 mRNA was abundantly expressed in tumor tissue as compared to adjacent normal tissues." (PMID 24454925, 2014). "For instance, Maulbecker and Gruss found that PAX6 induced tumor formation in mice." (PMID 24939714, 2014). "Given the reports that loss of PAX6 function leads to aberrant proliferation and immature differentiation of astrocytes in rodents, it is reasonable to assume that the PAX6 deletions contributed to the unusual proliferation of the tumor after its independent initiation." (PMID 20500513, 2010). "Similarly, most of the primary tumor samples showed high levels of PAX6 expression compared to GLI1 in the same samples." (PMID 21059263, 2010). "Therefore, it seemed that in the tumor cells, the PAX6 deletion extends more to 3′‐direction than that of the lymphocyte genome, or the tumor genome has an additional de novo deletion." (PMID 20500513, 2010). "PAX6 also inhibits glioma invasion and acts as a tumor suppressor gene." (PMID 21059263, 2010). "In this study, we detected an additional de novo PAX6 3’‐side deletion in patient's tumor cells." (PMID 20500513, 2010). "Next, we set out to determine whether the two different deletions of PAX6 in tumor genome are on the same chromosome or on different chromosomes." (PMID 20500513, 2010). "Given the fact that the PAX6 locus can be abnormally activated in tumors of many branched epithelial organs, this finding may have implications for the regulation of cell growth in other tumor cell types as well." (PMID 24586821, 2014). "Notably, it has also been reported that the PAX6 gene can possess both proto-oncogenic and tumor suppressor characteristics and these may vary among tumor types." (PMID 24810746, 2014). "In addition, this study also involved two new methylation markers, EVX2 and PAX6, which were highly specific for tumor-associated methylation, and little or no methylation was observed in tumor-adjacent normal lung tissue." (PMID 21507233, 2011). "We further validated the expression of Chromogranin A, Synaptophysin, PAX6 and NCAM1 using immunohistochemistry staining on MAP model tumor sections." (PMID 38609433, 2024). "Expression of radial glial cell signature genes (PAX6, SOX2, FABP7) and FGFR3 was confirmed in both the radial glial/astrocyte-like and tumor cell clusters, whereas PIK3R3 and AKT1 were only expressed in the tumor cell cluster." (PMID 38609519, 2024). "Analysis of the online data revealed that PAX2 and PAX8 were expressed at relatively high levels in RCC tumor tissues compared to other PAX genes, while PAX6 was expressed at lower but still significant levels." (PMID 37511191, 2023). "This action of circ007293 increases the expression of paired box 6 (PAX6) in PTC cells and promotes the EMT of tumor cells." (PMID 37046817, 2023). "PAX6 expression in the maintenance of neuronal cells and its apoptotic effect in GBM tumor cells are also very important in signifying the impact of cell type specific genetic programming in disease predisposition." (PMID 35538578, 2022). "Gene expression comparison between U-118 MG cells and the tumor showed an increased expression of neuronal and neural stemness genes MAP2, NEUN, ROBO2, PAX6, ZIC1, ZEB2, as well as MYC and OCT4 in tumor." (PMID 33468253, 2021).